MMP13 (matrix metallopeptidase 13)
Diseases named in the same sentence as MMP13 in open-access papers (continued):
Sharing a sentence is not in itself a finding about the gene and the disease.
breast carcinoma (continued). "MMP-13 promotes tumor growth and progression by mediating ECM reorganization and regulating the biological activity of cytokines in skin squamous cell carcinoma, melanoma, breast cancer and colorectal cancer." (PMID 21726449, 2011). "Recent data also show that tumour-derived, rather than stromal fibroblast-derived, MMP-13 correlates with aggressive breast tumour types and is inversely correlated with the overall survival of breast cancer patients." (PMID 19243594, 2009). "MMP-13 is over-expressed in breast carcinomas but not in normal mammary gland nor in benign mammary lesions." (PMID 18554405, 2008). "Tumor-derived, but not stromal fibroblast-derived, MMP-13 correlated with aggressive tumor phenotypes, and inversely correlated with the overall survival of breast cancer patients." (PMID 18373849, 2008). "In this study, we analyzed the effects of absence of MMP13 activity on the progression of MMTV-PyMT mammary carcinoma." (PMID 18698413, 2008). "We therefore conclude that the absence of MMP13 does not affect lung metastasis in the MMTV-PyMT breast cancer model." (PMID 18698413, 2008). "Accordingly, it has been reported that several other MMPs and TIMPs may be overexpressed and/or related to clinical outcome in breast cancer, such as MMP-11 MT1-MMP (MMP-14) MMP-13, TIMP-1 or TIMP-2." (PMID 17848954, 2007). "Notably, C7, MMP13, and PLAU have been reported as promoters of breast cancer progression." (PMID 41150812, 2025). "One study showed a significant association between stromal MMP-13 expression and poor prognosis but another study showed that tumoral MMP-13, not stromal fibroblast-derived MMP-13, correlated with aggressive tumor phenotypes and was an independent negative prognostic factor for OS in breast cancer." (PMID 36741729, 2022). "Interestingly expression of MMP13 alone is not sufficient to reverse the inhibition of breast cancer cell metastasis to the lung due to the expression of RKIP." (PMID 26308852, 2015). "Our transcriptome analysis data of human breast cancer tissues suggests a potential link between the spatial growth patterns and the expression levels of extracellular matrix remodeling genes such as MMP13 which show a significant negative correlation with the SED." (PMID 26669540, 2015). "Whereas MMP-13 expression (but not MMP-1 expression) was significantly and independently associated with the occurrence of distant metastasis in breast cancer, MMP-1 expression was strongly associated with the metastatic progression across the axillary lymphatic system." (PMID 25527274, 2014). "Therefore, models in which transition from DCIS to invasive carcinoma occurs similar to in human tumors are needed to definitely rule out a role of MMP13 in breast cancer." (PMID 18698413, 2008). "In addition, co-culture of breast cancer cells and osteoblasts has revealed that MMP-13 expression can be induced in osteoblasts by soluble factors produced by breast cancer cell lines, suggesting the involvement of osteoblastic MMP-13 in bone metastasis of breast cancer." (PMID 36741729, 2022). "Conditioned medium from breast cancer cells transfected with miR-124 inhibited the expression of MMP-13 in MC3T3 osteoblasts when compared to a control, which could, further on, indirectly reduce osteoclast activity and have consequences on the establishment of breast cancer bone metastasis." (PMID 35158995, 2022). "The biological activity of MMP-13 in tumor progression may not be limited to breast cancer." (PMID 18373849, 2008). "Furthermore, it is not clear whether MMP-13 can be used as an independent breast cancer biomarker." (PMID 18373849, 2008).
Arthritis (82 papers, 2005 to 2025). Inflammation of a joint. "MMP-13 deficiency in the K/BxN serum-transfer arthritis model, as well as selective MMP-13 inhibitor treatment in severe combined immunodeficiency and CIA models resulted in significantly reduced joint inflammation and cartilage destruction." (PMID 30949048, 2019). "Irreversible cartilage collagen breakdown by the collagenolytic matrix metalloproteinases (MMPs)-1 and MMP-13 represents a key event in pathologies associated with tissue destruction such as arthritis." (PMID 30440036, 2018). "Matrix metalloproteinase 13 (MMP-13) degrades collagenous extracellular matrix and its aberrant activity associates with diseases such as arthritis, cancer, atherosclerosis and fibrosis." (PMID 27084377, 2016). "Rankl mRNA expression was significantly enhanced by arthritis induction in both WT and M3R-deficient mice, but same as for Mmp13 mRNA, M3R-deficient mice reached higher expression levels of Rankl already in paws with low arthritis score." (PMID 26785775, 2016). "Mmp13 mRNA expression in paws was markedly enhanced by arthritis induction in both WT and M3R-deficient mice." (PMID 26785775, 2016). "Here we show that MMP-13 expression is increased in C57BL/6 mice during the course of the K/BxN serum-induced arthritis and that mice deficient for MMP-13 (MMP-13–/–) are protected from inflammation and joint destruction." (PMID 24369907, 2013). "Our results correspond well to studies in other mouse models that have implicated MMP-13 in development of arthritis." (PMID 24369907, 2013). "These potentially include NO production via rhythms in Nos2 expression and rhythmic MMP3 production, both previously linked to arthritis-associated joint damage and regulation of inflammation, as well as other inflammation-associated disease effectors (Cxcl5, Ccl20, Mmp13, Rankl/Tnfsf11)." (PMID 38981514, 2024). "Interestingly, in M3R-deficient mice, mRNA expression of Mmp13 was already prominently induced in paws with low arthritis scores while in WT animals only paws with an arthritis score > 4 showed high levels of Mmp13." (PMID 26785775, 2016). "Elevation of ucOCN levels led to the downregulation of COL10a1 and MMP13 expression, accompanied by a marked improvement in cartilage integrity in murine models of arthritis." (PMID 40765832, 2025). "To determine the specific activity of key MMPs implicated in arthritis, we performed ELISAs for MMP1, MMP3, and MMP13." (PMID 40491903, 2025). "In intervertebral disc degeneration, Mmp13 expression quantity significantly increases in IDD as well as in arthritis." (PMID 38243334, 2024). "Knocking out WTAP in chondrocytes decreased the m6A level and significantly decreased the mRNA (ADAMTS4, ADAMTS5, MMP13, IL-6, IL-8, iNOS) and protein levels of arthritis-related genes (ADAMTS4, ADAMTS5, MMP13) in the OA cell model." (PMID 38172596, 2024). "In the ERN1 cKO ACLT mouse model, more severe loss of proteoglycan in safranin O staining, a significantly higher arthritis score, elevated expression of MMP13 and ADAMTS5, and reduced expression of aggrecan and Col2 were observed." (PMID 37907740, 2023). "Cinnamaldehyde can not only significantly reduce the IL-6 content of inflammatory mediator TNF-α in peripheral mononuclear cells of RA patients, but also inhibit the release of IL-1β and matrix MMP-13 from synovial fibroblasts in arthritis patients." (PMID 37033930, 2023). "al reported that cartilage-specific overexpression of MMP13 induces cartilage degeneration in precocious arthritis." (PMID 36494653, 2022). "Alongside collagen synthesis marker suppression, the expression of Mmp13 was congruently elevated in mutant animals during acute arthritis." (PMID 35036874, 2022). "K/BxN serum-induced arthritis increases MMP-13 expression in C57BL/6 mice, and MMP-13-deficient (MMP-13−/−) mice exhibit reduced inflammation and joint destruction." (PMID 36051622, 2022).
Arthritis (continued). "Interstitial collagenase (MMP-1), stromelysin-1 (MMP-3), and collagenase 3 (MMP-13) appear to degrade the components of the cartilage ECM in arthritis." (PMID 32937098, 2021). "Clinical data have shown that MMP3 and MMP13 are highly expressed in the cartilage of patients with arthritis, resulting in OA progression." (PMID 33809253, 2021). "MMP-13 is highly expressed in arthritis patients, which can effectively degrade various collagens, and has a certain damage effect on articular cartilage." (PMID 34926690, 2021). "We found markedly increased levels of MMP9 and MMP13 in KLF2−/− mice compared to KLF2+/+ mice after induction of arthritis." (PMID 31426355, 2019). "The importance of MMP-13 in cartilage degradation in arthritis was demonstrated in transgenic mice overexpressing MMP-13 and elevated levels of MMP-13 were found in synovial fluid of arthritic patients." (PMID 31067826, 2019). "Emerging evidence from OA patients and rodent experimental arthritis supports that MMP13 plays a crucial role in the disease development and is believed as an important biomarker to reflect arthritis progress and therapeutic effects." (PMID 29899528, 2018). "For example MMP-13, the key player in collagen degradation and a valid target for arthritis and cancer, can be inhibited selectively and with high affinity with a variety of ligands." (PMID 32961647, 2017). "MMP-13 is within the enzyme class the most efficient contributor to type II collagen degeneration and is a validated target in arthritis and cancer." (PMID 32961647, 2017). "Because abnormal expression of mmp9 and mmp13 occurs in human diseases such as cancer, arthritis and cardiovascular disorders, small molecule inhibitors specific to MMP9 and MMP13, respectively, or to both MMP9 and MMP13 were available." (PMID 28158191, 2017). "MMP-14 is upregulated in arthritic cartilage and furthermore appears to have the ability to activate MMP-2 and MMP-13, potentially compounding its influence in arthritis." (PMID 27478294, 2016). "MMP13 is not only an important factor for cartilage degradation in arthritis, but additionally plays an essential role for the inflammatory response and bone degradation." (PMID 26785775, 2016). "MMP-13 is expressed in a very restricted manner in the human body, but is often upregulated under pathological conditions, such as cancer and arthritis." (PMID 26378022, 2015). "We found that inhibition of IL-17 during established arthritis caused only a modest decrease in the local expression of MMP3, MMP13 and IL-23, but a marked reduction in systemic IL-6 levels, in accordance with previous reports." (PMID 26081345, 2015). "Semi-quantitative polymerase chain reaction analysis showed that MMP-13 expression increased on day 3, and was highest on day 8 after arthritis induction." (PMID 24369907, 2013). "We observed increased expression of MMP-13 in ankle joints of WT mice during K/BxN serum-induced arthritis and both K/BxN serum-treated WT and MMP-13–/– mice developed progressive arthritis with a similar onset." (PMID 24369907, 2013). "Both the control C57BL/6 mice and the MMP-13–/– mice developed arthritis within 2 days after K/BxN serum transfer." (PMID 24369907, 2013). "The onset of arthritis occurred 2 days after injection of sera in both WT control mice and MMP-13–/– mice." (PMID 24369907, 2013). "In contrast, MMP-13–/– mice displayed significantly decreased severity of arthritis (50% to 60%) as analyzed by clinical and histological scoring methods." (PMID 24369907, 2013). "Our data demonstrate that MMP-13 is required for a sustained inflammatory response that occurs in the effector phase of arthritis and suggest a role for MMP-13 apart from cartilage destruction in modulating the inflammatory response." (PMID 24369907, 2013). "This study clearly shows that MMP-13 promotes inflammation and joint destruction in the K/BxN serum-induced arthritis model." (PMID 24369907, 2013).
Arthritis (continued). "In this study we tested the role of MMP-13 using MMP13–/– mice in an antibody-induced arthritis model." (PMID 24369907, 2013). "Pharmaceutical inhibition of MMP-13 resulted in reduced arthritis in the collagen-induced arthritis and severe combined immunodeficiency mouse coimplantation model, but not in the antibody-induced arthritis model." (PMID 24369907, 2013). "The increase in MMP-13 expression correlated positively with the increase in ankle measurement and histological scores observed in mice after arthritis induction." (PMID 24369907, 2013). "Arthritis was induced in C57BL/6 wild type (WT) and MMP-13-deficient (MMP-13–/–) mice by intraperitoneal injection of 200 μl of K/BxN serum." (PMID 24369907, 2013). "To understand better the role of MMP-13 in arthritis development and progression we studied the role of MMP-13 in the K/BxN serum-induced arthritis model." (PMID 24369907, 2013). "In a murine type II collagen-induced arthritis, it was found that NF-kB expression correlated with MMP-13 and MMP-3 levels leading to cartilage destruction and articular damage." (PMID 22146575, 2011). "Selective MMP13-specific protease inhibitors are already developed and are currently used in mouse models for arthritis." (PMID 20667128, 2010). "MMP-13 imbalance is also observed in the course of another bone disease, arthritis." (PMID 41450968, 2025). "Similarly, OPCs protect cartilage by inhibiting synovitis, subchondral fractures, and cartilage damage, while reducing reactive oxygen species (ROS) production and MMP13 expression in monosodium iodoacetate (MIA)-induced arthritis in rats." (PMID 40284819, 2025). "HSP90AB1 may inhibit the upregulation of MMP-13 from mitigating transitional degradation of articular cartilage in arthritis." (PMID 37779906, 2023). "When calcitriol is used in the treatment of knee osteoarthritis, it can inhibit MMP by inhibiting MMP-1, MMP-3, and MMP-13 gene expression, thereby reducing the severity of arthritis in patients, reducing pain in patients, and improving the living conditions of patients." (PMID 36091601, 2022). "Therefore, this study demonstrates that an equal ratio of n-6 and n-3 PUFAs is the most effective in inhibiting MMP-13 expression and induced arthritis in rats, thus, representing a good approach for the treatment of OA symptoms." (PMID 34925695, 2021). "Therefore, the identification of IL-33 as a stimulus of MMP-1 and MMP-13, and the elucidation of its mechanisms of induction and action, provide new insights into the promotion of arthritis responses by the innate immune system." (PMID 29095435, 2017). "Expression of MMP2, MMP9, and MMP13 genes, which are related to the endochondral ossification pathway and bone remodeling, was also increased in the arthritic paw up to day 8 after arthritis induction." (PMID 26801240, 2016). "Such specificity of inhibition may become a major shift in arthritis treatment, because the collagen degradation is mainly initiated by MMP-13." (PMID 25992888, 2015). "The result also found that PAR1/PAR3 receptors activation by MMP-13 is increased by thrombin via a mechanism involving EGFR transactivation and activation of PKCδ, c-Src, PI3K, Akt, and finally AP-1 on the MMP-13 promoter, thereby contributing to cartilage destruction during arthritis." (PMID 25313362, 2014). "We induced arthritis using the K/BxN serum in the MMP-13–/– mice and in the control C57BL/6 mice." (PMID 24369907, 2013). "Our results provide evidence that thrombin acts through the PAR1/PAR3 receptors and activates PKCδ and c-Src, resulting in EGFR transactivation and activation of PI3K, Akt, and finally AP-1 on the MMP-13 promoter, thereby contributing to cartilage destruction during arthritis." (PMID 24385683, 2013). "In this study we investigated the role on MMP-13 in the K/BxN sera-transfer arthritis model." (PMID 24369907, 2013). "Our studies clearly show that deletion of MMP-13 attenuates arthritis progression in mice." (PMID 24369907, 2013).
Arthritis (continued). "To determine whether the expression of MMP-13 was upregulated during arthritis development, we examined its expression in the joints by polymerase chain reaction." (PMID 24369907, 2013). "Matrix metalloproteinase-13 (MMP-13) may contribute to the breakdown of articular cartilage during arthritis." (PMID 24385683, 2013). "However, in contrast to WT mice, MMP-13–/– mice showed reduced arthritis severity with average ankle thickness and clinical index decreased by 1.4-fold (P <0.001) and 1.5-fold (P <0.001) respectively when compared with the WT mice." (PMID 24369907, 2013). "Therefore, MMP-13 has a role in the pathogenesis of arthritis, suggesting MMP-13 is a potential therapeutic target." (PMID 24369907, 2013). "MMP-13 inhibition may thus have potential for the treatment of arthritis progression, and the K/BxN serum-induced arthritis model will serve as a useful tool to study the efficiency of MMP-13 inhibitors in treating arthritis." (PMID 24369907, 2013). "MMP13, also called collagenase-3, is expressed in a very restricted manner in the human body, but is often upregulated under pathological conditions, such as cancer and arthritis." (PMID 20667128, 2010). "MMP13 levels are increased in cartilage and synovium of patients with arthritis." (PMID 20691044, 2010). "Other identified target genes included MMP13 and MMP14 of the metalloproteinase family, involved in tissue remodeling and cartilage degradation, which are activated in non-pathological post-exercise conditions but can be associated with pathologic processes, including tumor invasion and arthritis." (PMID 37445763, 2023). "Since MMP-13 expression increases in OA chondrocytes, the effects of different n-6/n-3 PUFAs ratios were studied both in vitro (in inflammatory human chondrocytes) and in Sprague-Dawley rats with arthritis induced by Freund's complete adjuvant, treated for six weeks." (PMID 34925695, 2021). "In addition to MMP13, some of these OA-responsive DEGs shared by cartilage and synovium have also been studied in the arena against arthritis, although their function may only be investigated solely in cartilage or synovium." (PMID 32842604, 2020). "Gain or loss of function from individual arthritis-related miRNAs such as miR-155 could also lead to similar expression regulation of proinflammatory proteins including MMP3 and MMP13, which suggested that partial function of DICER1 could be achieved through its downstream miRNAs." (PMID 31275058, 2019). "Interestingly, Mmp13 and Mmp9 induction are also found in patients with arthritis; these individuals also have abnormal matrix, and could share the same pathogenetic mechanism." (PMID 28158191, 2017). "Moreover, in arthritic M3R−/− mice, mRNA expression of MMP13 was already strongly enhanced in paws with low arthritis score, when compared to WT mice with CAIA, indicating that collagen II degradation might be stronger in M3R-deficient mice." (PMID 26785775, 2016). "Additionally to MMP13, mRNA expression of cathepsin K and RANKL was already strongly increased in M3R-deficient paws with low arthritis score, while in WT animals enhanced expression was only observed in paws with high arthritis score." (PMID 26785775, 2016). "Notably, this anti-inflammatory effect of PPARγ ligands extends to the inhibition of IL-1β-induced expression of MMP-1 and MMP-13 in rabbit chondrocytes, and administration of these compounds blunts the development of joint disease in animal models of arthritis." (PMID 19046432, 2008). "Our results indicated a significant decrease in MMP-13 expression in the HDF group compared to the NDF group, indicating a reduction in arthritis-related inflammation." (PMID 38803575, 2024). "After 10 weeks of loganin treatment, arthritis was evaluated histologically by safranin O staining; immunohistochemistry of COX-2, MMP-3, and MMP-13; and micro-computed tomography (micro-CT)." (PMID 33567513, 2021).